SIRT7 (sirtuin 7)
Diseases named in the same sentence as SIRT7 in open-access papers (continued):
Sharing a sentence is not in itself a finding about the gene and the disease.
tumor (continued). "However, because SIRT7 promotes tumor progression through mechanisms that extend beyond its enzymatic activity, pharmacological inhibition of its catalytic function alone may be insufficient to achieve durable therapeutic effects." (PMID 41471367, 2025). "Notably, the EZH2 expression pattern in tumor tissues was similar to that of SIRT7, suggesting that only the shRNA EZH2 lentivirus treatment could alter the EZH2 expression levels." (PMID 39719443, 2024). "Specifically, SIRT1, SIRT2, SIRT6, and SIRT7 are implicated in promoting PCa progression, while SIRT5 displays a paradoxical role, simultaneously aiding DNA repair and inhibiting apoptosis, yet fostering tumor growth through androgen receptor (AR) interactions." (PMID 39796040, 2024). "Interestingly, recent studies elucidating the expression profiles of sirtuins in PDAC revealed that low levels of nuclear SIRT7 correlate with more aggressive tumor phenotypes and poorer patient outcomes, thus establishing it as a significant biomarker for disease prognosis." (PMID 39682281, 2024). "IRE1α could also regulate the expression and secretion of cytokines via XBP1 to promote tumor cell survival under ER stress, especially tumor-promoting factors like TNFα, IL-8, and VEGFα.40,41 Therefore, we wondered whether SIRT7 also regulated these cytokines with oncogenic function." (PMID 36918544, 2023). "Therefore, SIRT4 and SIRT5 potentially inhibit the occurrence and development of ccRCC, whereas high expression of SIRT3, SIRT6, and SIRT7 might have an important tumor-promoting role." (PMID 37096064, 2023). "In addition, SIRT7 may exert its oncogenic properties through the upregulation of ribosomal RNA synthesis to meet the increased demand for ribosomes in rapidly growing tumor cells." (PMID 36429037, 2022). "Therefore, we reasoned that the GSK3β–SIRT7 axis might inhibit tumor progression via AKT inactivation." (PMID 34433808, 2021). "Importantly, analysis of the tumor xenografts showed that endogenous SIRT7 (mSIRT7) expression remained low, suggesting that this effect is determined by ectopic expression of relevant SIRT7 mutants." (PMID 34433808, 2021). "Thus, our findings indicate that targeting the GSK3β–SIRT7 axis might recapitulate the effects of fasting on tumor growth and metastasis." (PMID 34433808, 2021). "Our data showing that Sirt7 expression was decreased during tumor progression suggest that the GSK3β–SIRT7 axis might be hijacked by oncogenic signaling to facilitate tumor initiation and malignancy." (PMID 34433808, 2021). "Interestingly, the roles of SIRT7 in tumor development are also hotly debated." (PMID 34433808, 2021). "However, the potential functions of SIRT7 in tumor progression and tumor immune response remain unclear." (PMID 32528869, 2020). "Although the mechanism of SIRT7 deregulation in BlCa remains elusive, it is tempting to speculate whether it might be due to epigenetic mechanisms, which allow for the suggested plasticity of SIRT7 gene expression during carcinogenesis and tumor progression." (PMID 32344886, 2020). "Therefore, the tumor-promoting performance of SIRT7 may be a secondary effect most likely due to its positive impact on ribosome biogenesis." (PMID 31817470, 2019). "Functionally, SIRT7 inhibition enhanced radiation-induced DNA damage and apoptosis in a partially MEN1-dependent manner and significantly suppressed tumor growth in patient-derived organoids and multiple independent xenograft models." (PMID 41972414, 2026). "In contrast, a recent study reported that dependent on SIRT7-mediated PRMT5 K387 desuccinylation in tumors, PRMT5 contributes lipid metabolic reprogramming, tumor development, and metastasis, which is consistent with our study." (PMID 40777599, 2025). "We discovered that protein modification-related, including HDGF, SIRT-7, UBE2A, and UCHL5, elevated expression in tumor tissues." (PMID 40041484, 2025).
tumor (continued). "While SIRT3, SIRT4, and SIRT6 are poised to induce tumor-suppressive autophagy, others, such as SIRT2 and SIRT7, are likely to stimulate protective autophagic programs that underlie tumor survival and drug resistance." (PMID 41425553, 2025). "SIRT7 deacetylates and stabilizes USP39, enhancing FOXM1 transcriptional activity and thereby stimulating tumor growth through the autophagic regulation of redox homeostasis." (PMID 41425553, 2025). "While SIRT1, SIRT2, and SIRT6 can assume opposite functions in relation to the tumor context, SIRT3, SIRT4, and SIRT7 tend to function more in favor of tumors." (PMID 41425553, 2025). "Concurrently, kaempferol, which acts as a regulator of SIRT7, was found to enhance the Kcr level of MCM6, reducing tumour weight, particular when combined with paclitaxel, highlighting its potential chemotherapeutic target for BRCA therapy." (PMID 39477811, 2025). "Specifically, SIRT7 acts as a desuccinylase targeting MVP at K437, which in turn activates JAK2/STAT3 signaling to drive tumor cell proliferation, migration, and invasion." (PMID 40586636, 2025). "For example, SIRT7 has been shown to repress succinylation of KIF23, affecting cell cycle progression and tumor growth." (PMID 40586636, 2025). "SIRT7 influences fatty acid biosynthesis by modulating BCAA catabolism in lymphocytes, thereby affecting T-cell activation and anti-tumor immunity." (PMID 41471367, 2025). "We also assessed the SIRT7, EZH2, and RND3 protein levels in tumor tissues from each group of mice using IHC." (PMID 39719443, 2024). "SIRT7 appears to promote proliferation and survival of pancreatic ductal adenocarcinoma (PDA) by epigenetically repressing expression of tumor suppressors through H3K18 deacetylation." (PMID 38383727, 2024). "Scrambled, SIRT7 KD, ARF KD, and SIRT7/ARF dKD H1299 cells, labeled by expression of EGFP, were subcutaneously injected into nude mice and tumor growth was monitored by fluorescence imaging every 4 d starting from day 14 after injection." (PMID 38870055, 2024). "With the exception of HDAC1, SIRT6, and SIRT7, most HDAC genes were down-regulated in various tumor types." (PMID 39512688, 2024). "In tumor-bearing mice, silencing of SH3PXD2A-AS1 suppressed tumor growth and the protein levels of Ki67, SIRT7, and FOXM1." (PMID 39020302, 2024). "However, SIRT7 may also abrogate other critical tumor suppressive functions of ARF." (PMID 38870055, 2024). "Studies have shown that the expression of SIRT2, SIRT3, SIRT6, and SIRT7 is increased in tumor-stage 1-4 subgroups, SIRT1 expression is increased in tumor-stage 1, and the expression of SIRT4 is decreased." (PMID 37096064, 2023). "We the evaluated the correlation between SIRT7 and USP39 and a positive correlation between the expression of SIRT7 and USP39 was verified in the tumor tissues of CSCC patients." (PMID 37957720, 2023). "Mechanistically, SIRT7 selectively activated the IRE1α-XBP1 axis to potentiate the pro-survival ERK signal pathway and the secretion of tumor-promoting cytokines like IL-8, TNF-α and VEGFA." (PMID 36918544, 2023). "Mechanistically, SIRT7 selectively activated the IRE1α-XBP1 axis to potentiate the pro-survival ERK signal pathway and the secretion of tumor-promoting cytokines." (PMID 36918544, 2023). "SIRT7 also boosts tRNA transcription via Pol III and inhibits ELK4 and MYC transcription, thus promoting tumor growth." (PMID 36499440, 2022). "We next overexpressed human SIRT7-WT, SIRT7-2A, or SIRT-2E in 4T1 cells stably expressing KD7 (shSirt7) and observed their effects on tumor progression." (PMID 34433808, 2021).
tumor (continued). "Although the mechanism of dysregulation of SIRT7 in BC and its putative implication in metabolic rewiring have not yet been adequately addressed, it is speculated that this could be due to epigenetic mechanisms that allow a plastic expression of SIRT7 in both carcinogenesis and tumor progression." (PMID 34072826, 2021). "The expression levels of SIRT3 and SIRT7 were correlated with high Ki-67 expression, i.e., a high proliferation rate, in GCT samples, implying roles in tumor cell proliferation." (PMID 33669567, 2021). "At the molecular level, SIRT7 suppresses SCF-SKP2 E3 ligase-mediated AKT ubiquitination, thus antagonizing the function of AKT in tumor growth and distal organ metastasis." (PMID 34433808, 2021). "We recently demonstrated that sirtuin 7 (SIRT7) activates this pathway by directly deacetylating NPM following ultraviolet irradiation, indicating tumor-suppressive functions of SIRT7." (PMID 34027038, 2021). "However, the potential functions of SIRT7 in tumor progression and tumor immunology remain unclear." (PMID 32528869, 2020). "Immunohistochemical (IHC) analysis showed that the animals injected with SIRT7-depleted 22Rv1 cells had a lower percentage proliferation of Ki67+ and LC3+ tumor cells than mice administered wild type 22Rv1 cells." (PMID 32019578, 2020). "In HCC, SIRT7 expression was upregulated in a large cohort of HCC patents and SIRT7 expression is regulated by the tumor suppressors miR-125a and miR-125b." (PMID 31196136, 2019). "SIRT7 expression and higher H3K18ac levels were observed in HCC cells compared to non-tumor hepatocytes, and SIRT7 expression was weakly correlated with H3K18Ac." (PMID 31121824, 2019). "Evaluating with Oncomine data, we found most target genes (BCL2, ERBB2/3, SIRT7, ETS1, Mcl-1, IL6R, and LIN28B) were significantly activated in HCC tumor tissues, consistent with miR-125b underexpression." (PMID 25861255, 2015). "Subsequently, we evaluated the tumor’s responses to temozolomide (TMZ) by comparing the scenarios in which SIRT7 was silenced with those in which it was not." (PMID 41114868, 2025). "Furthermore, the flavonoid kaempferol has been identified as a modulator of SIRT7, enhancing MCM6 Kcr levels and reducing tumor weight." (PMID 40165597, 2025). "Kaempferol, which acted as a regulator of SIRT7, could enhance MCM6 Kcr level, alleviating tumour weight, especially combined with paclitaxel, which presents a potential chemotherapeutic target for BRCA therapy." (PMID 39477811, 2025). "Rather than functioning as a simple tumor suppressor or promoter, SIRT7 acts as a context-dependent molecular rheostat, balancing cellular resilience with immune recognition." (PMID 41471367, 2025). "Proteins such as SIRT7 inhibitors and targeting ligands like SP94 were incorporated to improve drug sensitivity and tumor targeting, while polymeric and functionalized NP platforms enabled controlled, responsive drug release in the tumor microenvironment." (PMID 40278256, 2025). "In non-malignant cells, SIRT7 preserves genome integrity by activating multiple DNA repair pathways and stabilizing chromatin, thereby functioning as a tumor suppressor." (PMID 41471367, 2025). "Notably, under CDDP treatment, the combined application of the SIRT7 shRNA and EZH2 shRNA lentiviruses markedly enhanced the tumor RND3 protein levels compared to the administration of either shRNA lentivirus alone." (PMID 39719443, 2024). "Furthermore, the administration of the shRNA SIRT7 and shRNA EZH2 lentiviruses, along with CDDP, resulted in the most pronounced tumor growth inhibition effect in mice." (PMID 39719443, 2024). "SIRT7 catalyzes the desuccinylation of PRMT5, thereby augmenting its methyltransferase activity and inhibiting its ubiquitination, thereby promoting lipid metabolic reprogramming, tumor growth, and tumor metastasis in HCC." (PMID 39519130, 2024).
tumor (continued). "SIRT7 also enhanced distal Igh recombination in pro-B cells and behaved as a tumor suppressor in B-ALL, suggesting that SIRT7 may contribute to the prevention of malignant transformation in hematopoietic progenitors." (PMID 39424985, 2024). "SIRT6 and SIRT7, through their roles in angiogenesis, EMT, and metastasis, represent additional targets, with modulators of SIRT6, such as JYQ-42, showing potential to reduce tumor invasiveness." (PMID 39682281, 2024). "Furthermore, the concurrent administration of the shRNA SIRT7 and shRNA EZH2 lentiviruses resulted in the most significant enhancement in the CDDP treatment-induced tumor tissue weight reduction." (PMID 39719443, 2024). "Our results based on the clinical-pathological characteristics of patients with ccRCC showed that the expression of SIRT2, SIRT3, SIRT6, and SIRT7 was increased in tumor-stage 1-4 subgroups, SIRT1 was increased in tumor-stage 1, and the expression of SIRT4 and SIRT5was decreased." (PMID 37096064, 2023). "However, there is quite a consensus in the literature that HDAC4, HDAC7, HDAC9, SIRT2, and SIRT7 are upregulated in GC and seem to be pro-tumor factors, whereas SIRT4, SIRT5, and SIRT6, which are downregulated, seem to have a tumor suppressor function." (PMID 36358890, 2022). "In the four groups of nude mice transplanted with malignant cells, the two groups overexpressing miR-148b (with or without SIRT7 overexpression) had lower weight and smaller volume of the tumor than the LV-SIRT7 and LV-control groups." (PMID 33274232, 2020). "SIRT7 may be an unfavorable prognostic factor for KIRC and high SIRT7 expression was positively correlated with tumor pathologic stage and histological grade." (PMID 32158696, 2020). "Compared to healthy glands specimens, the expression of SIRT7 mRNA in some tumor specimens was not significantly increased but the expression of protein was higher." (PMID 32019578, 2020). "As expected, we found an up-regulation of AMACR expression in the tumor compared to the healthy gland whereas the expression of SIRT7 mRNA did not vary." (PMID 29100388, 2017). "Similar to the other Sirts, Sirt7 has been considered a tumor suppressor and its activity is mediated by the negative regulation of HIF1 and HIF2 transcription." (PMID 27379175, 2016). "Multivariate cox–regression analysis revealed that nuclear SIRT7 expression (p = 0.023) and lymph node status (p = 0.004) were independent of tumour differentiation, stage and grade, in influencing disease-free survival." (PMID 26121130, 2015). "Multivariate cox—regression analysis revealed that nuclear SIRT7 (p = 0.020) and lymph node status (p = 0.007) were independent of tumour differentiation, grade and size, in influencing time to death." (PMID 26121130, 2015). "This interplay between SIRT7 and MYC might suggest that SIRT7 functions as a tumor suppressor by inhibiting MYC activity, similar to SIRT6." (PMID 25085992, 2014). "Similar to ARF, SIRT7 may regulate the activity of other nucleolar proteins to influence tumor progression through mechanisms that may or may not depend on its catalytic activity." (PMID 39036727, 2024).
tumor (continued). "Combined with SIRT expression (mRNA and protein) and the prognostic value of SIRTs (mentioned previously herein), we speculate that SIRT4 and SIRT5 might be possible tumor suppressor markers, whereas SIRT6 and SIRT7 could play an important role in promoting tumor development." (PMID 37096064, 2023). "However, the overall role of SIRT7 in cellular plasticity was not demonstrated and a decrease in tumor size after SIRT7 knockdown was not very appreciable." (PMID 32656073, 2020). "Interestingly, SIRT7 expression was found to be higher in tumor samples rather than in normal tissue, and its levels were dramatically elevated in metastatic tissue as compared with primary tumors." (PMID 27379175, 2016). "Therefore, it can be proposed that NF-κB p65 might also indirectly promote PD-L1 expression via SIRT7 and its-mediated IRE1α-XBP1 axis, and this speculation might provide more evidence supporting the role of NF-κB p65 in anti-tumor immunity, which needs more investigation in the future." (PMID 36918544, 2023). "In addition, the combination of the knockdown of SIRT7 and anti-PD-1 antibody treatment could induce more infiltration of CD8+T cells and GzmB-positive CD8+T cells in the implanted tumor, indicating that the combination treatment approach triggered more prominent activation of anti-tumor immunity." (PMID 36918544, 2023). "In addition, we observed that double knockdown of SirT7 significantly reduced 2DG-induced cell death in stable REGγ-knockdown HCT116−/− cells, suggesting that endogenous SirT7, at least in part, contributes to energy stress induced tumour cell death in REGγ-knockdown cells." (PMID 27511885, 2016). "Furthermore, in an allograft tumor model, immune-competent mice engrafted with HCC cells that lacked SIRT7 gene expression had significantly higher PD-L1 levels than those engrafted with control HCC cells." (PMID 38316768, 2024).
metabolic disorders (7 papers, 2022 to 2026). "Meanwhile, following EMPA treatment, Nrf1 upregulation enhanced SIRT7 signaling pathway activation, protected against lipid deposition-related metabolic disorders, and inhibited lipogenesis and oxidative stress." (PMID 40362294, 2025). "SIRT7, as a brake-switch of energy consumption, will hopefully be a potential target for the treatment of metabolic disorders." (PMID 36509749, 2022). "Indeed, investigating the relationship between NRF1 and SIRT7 is essential for understanding metabolic diseases and developing potential treatments for obesity and T2DM." (PMID 40362294, 2025). "Because NF-κB plays an important role in many inflammatory and metabolic diseases, there is considerable interest in whether the inhibition of SIRT7 is useful for treating immune-mediated intestinal inflammation." (PMID 36359214, 2022). "SIRT1, SIRT6, and SIRT7 are nuclear proteins, and SIRT1 and SIRT6 exert beneficial effects against metabolic diseases." (PMID 36429037, 2022).
prostate (6 papers, 2015 to 2023). "Here, we demonstrated that SIRT7 is a key oncogene promoting prostate tumorigenesis." (PMID 32019578, 2020). "Nevertheless, in all those models, a strict oncogenic role was proposed for SIRT7, whereas our findings suggest that, at the least in bladder carcinogenesis, SIRT7 may play a dual role, eventually context-dependent." (PMID 32344886, 2020).